VTRNA1-1 (vault RNA 1-1)
Synonyms: hvg-1; HVG1; vRNA; VR1; VAULTRC1
Gene: Gene (Ensembl biotype vault_RNA) on chromosome 5 (140,711,275 to 140,711,373, forward strand). Ensembl gene ENSG00000199990.
Homologues: Orthologues: chimpanzee Vault (99% identical), macaque Vault (83% identical), guinea pig Vault (74% identical), pig Vault (74% identical), guinea pig Vault (71% identical), rabbit Vault (66% identical), rabbit Vault (63% identical). Paralogues in human: VTRNA3-1P (77% identical), VTRNA1-3 (72% identical), VTRNA1-2 (69% identical), Vault (63% identical), VTRNA2-2P (57% identical), Vault (53% identical), Vault (48% identical).
Diseases named in the same sentence as VTRNA1-1 in open-access papers:
VTRNA1-1 is named in the same sentence as 10 diseases in open-access papers, as found by Europe PMC text mining. Sharing a sentence is not in itself a finding about the gene and the disease. The quoted sentences say what the papers report.
hepatocellular carcinoma (2 papers, 2020 to 2024). A malignant tumor that arises from hepatocytes. "One of the most recent reports on vtRNA functions demonstrated an interaction of vtRNA1-1 with the autophagy receptor sequestosome-1/p62 in the human hepatocellular carcinoma cell line HuH-7." (PMID 32316166, 2020).
B cell lymphoma (1 paper, 2015). "This LMP1-dependent expression of vtRNA1-1 was also evident in several other B cell lymphoma lines." (PMID 25952297, 2015).
cervical cancer (1 paper, 2025). A primary or metastatic malignant neoplasm involving the cervix. "It has been reported that vtRNA1-1 modulates pro-survival characteristics in many cancer cell lines, deriving from lymphoma, lung cancer, and cervical cancer." (PMID 40096176, 2025).
liver cancer (1 paper, 2025). An epithelial or non-epithelial malignant neoplasm that arises from the liver. "In view of the fact that vtRNA1-1 and these two TRIM proteins are upregulated in liver cancer tissues, it is reasonable to assume that this RNA-protein complex makes an important contribution to liver cancer progression." (PMID 40096176, 2025).
cancer (6 papers, 2015 to 2025). A tumor composed of atypical neoplastic, often pleomorphic cells that invade other tissues. "One of the human vault RNA paralogs, vtRNA1-1, modulates several intracellular processes, including proliferation, apoptosis, autophagy, and drug resistance in various types of human cancer cells." (PMID 40096176, 2025). "For example, vtRNA2-1 inhibits proliferation of several cancer cells, including colon, lung, breast, skin, cervical, and oral cancers, while vtRNA1-1 regulates apoptosis and cancer invasion." (PMID 41373720, 2025). "Altogether, these studies revealed that, in cancer cells, vtRNA1-1 is an important contributor to proliferation and its absence impairs cell growth, thus possessing the characteristics of an oncogene." (PMID 35681764, 2022). "Previously, we demonstrated a role of the human non-coding vault RNA1-1 (vtRNA1-1) in inhibiting intrinsic and extrinsic apoptosis in several cancer cell lines." (PMID 32316166, 2020). "Even though a direct physical link between vtRNA1-1 and members of these signaling pathways awaits future characterization, our study substantiates a pro-survival role of this ncRNA in human cancer cells." (PMID 32316166, 2020). "Taken together, these findings indicate that vtRNA1-1 has an important impact on apoptosis resistance in different cancer cell types." (PMID 25952297, 2015). "vtRNA1-1 also regulates autophagy by associating with RBP p62, whereas vtRNA2-1 functions as a tumor suppressor by interacting with protein kinase R in a wide range of cancer cells." (PMID 41373720, 2025). "The development of small molecules targeting vtRNA1-1 indeed could represent an important step in cancer treatment, being able to potentiate the anti-tumor effect of currently available drugs such as Sorafenib and Mitoxantrone." (PMID 35681764, 2022). "As the here identified candidates VTRNA1-1, RNY1, and RNY4 have been suggested to distinguish cancer from normal counterparts, and VTRNA1-1 also to inhibit apoptosis and affect chemoresistance, they could have roles in the mechanisms that are involved also in the aggressiveness of TNBC." (PMID 36585466, 2022). "Thus, indicating an involvement of vtRNA1-1 in apoptosis resistance of different cancer cell types." (PMID 32316166, 2020).
tumor (2 papers, 2014 to 2022). "Despite our still limited knowledge of vtRNA1-1 role in anti-tumor drug resistance, these findings might open new appealing therapeutic scenarios in the pharmacology field." (PMID 35681764, 2022).
VTRNA1-1 also shares sentences with these, for which no sentence is quoted: breast carcinoma (1 paper); liver cirrhosis (1); lung carcinoma (1); lymphoma (1).